PPARA (peroxisome proliferator activated receptor alpha)
Diseases named in the same sentence as PPARA in open-access papers (continued):
Sharing a sentence is not in itself a finding about the gene and the disease.
cancer (continued). "Similarly, in weight stable Apc(min/+) mice, mitochondrial mRNA for Pgc‐1α, Pparα, and Mfn2 were significantly decreased in quadriceps, indicating that mitochondrial biogenesis is impacted prior to obvious body and muscle wasting in the development of cancer cachexia." (PMID 40985218, 2025). "The expression profiles of three PPAR genes (PPARA, PPARD and PPARG) were downloaded from The Cancer Genome Atlas (TCGA) dataset to analyze their expression patterns across pan-cancer." (PMID 38529307, 2024). "Together, they decrease transcription of the PPARα gene and further regulate PPARα target acyl-coenzyme A oxidase (ACO), cell cycle proteins D1 and P27, blocking the proliferation of cancer cells and promoting apoptosis." (PMID 38966543, 2024). "The possible molecular mechanism involves inhibiting cleaved CASP3, MMP3, SRC, MAPK10 and CDK6, and activating PPARα and JAK, which are typically involved in cancer pathways, the PI3K-Akt signaling pathway and viral carcinogenesis pathways." (PMID 38675723, 2024). "The possible molecular mechanism involved in cancer pathways, PI3K-Akt signaling pathway and viral carcinogenesis pathway via the inhibition of CASP3, MMP3, SRC, MAPK10 and CDK6 and the activation of PPARα and JAK." (PMID 38675723, 2024). "In summary, this study was the first to comprehensively analyze the expression patterns of PPARA, PPARD and PPARG in multiple cancers including in STAD." (PMID 38529307, 2024). "PPARA, PPARD and PPARG were more abnormally expressed in STAD samples and cell lines when compared to most of 32 type cancers in TCGA." (PMID 38529307, 2024). "By modulating a range of downstream genes, PPARα enhances FAO, providing cancer cells with the necessary energy and precursors to thrive, especially in hypoxic and nutrient-deprived environments." (PMID 39519311, 2024). "We observed that PPARA and PPARG genes were upregulated in most para-cancer samples, while PPARD was upregulated in cancer tissues." (PMID 38529307, 2024). "Antagonism, for most of the selected targets (genes in purple), and agonism, for PGR, PPARA, and VDR (genes in red), were proposed as potential approaches for anti‐aging and anti‐cancer treatment." (PMID 37888486, 2023). "Except for cancer, during hepatic lipid metabolism, miR-5194 distributing in the mitochondria activated ADIPOR1/PPARA signaling that sequentially accelerated fatty acid oxidation." (PMID 37215458, 2023). "Thus, tissue editing techniques disclose that the wide-ranging functions of PPARα/γ agonists in tumor tissues may be selectively focused on differential reprogramming patterns of cancer hallmarks, induction of tumor cell death, and on facilitating edited non-oncogene addiction." (PMID 38273846, 2023). "In a variety of cancer types, a considerable number of drugs that can inhibit the synthesis of SREBP, ACLY, ACC, FASN, SCD, and PPARα have been tested for anticancer effects in preclinical and clinical studies." (PMID 38189049, 2023). "Studies have demonstrated that PPARα and HMGCS2 directly interact, resulting in the activation of the proto-oncogene Src and promoting the growth and invasion of malignant tumors." (PMID 37251321, 2023). "PPARα is a critical regulator of enzymes in FAO and our results are in accordance with studies indicating that PPARα has a beneficial effect against cancer." (PMID 35898887, 2022). "In other studies, in which the role of PPARα was investigated in cancer, GW6471 (a PPARα selective antagonist) reduced tumor cell viability, interfering with the cell cycle and inducing apoptosis." (PMID 36313013, 2022). "Multiple studies have shown that peroxisome proliferator-activated receptors (PPARs, including PPARα, PPARβ and PPARγ), markers of lipid metabolism-related signalling pathways, are activated by FABP5 and are involved in the progression of human cancers." (PMID 36168624, 2022).
cancer (continued). "We suggest that RV directly modulates PPARα-mediated L1-RTP in somatic cells and that MAPK signaling closely interacts with SIRT6 preventing human diseases, such as cancer and sporadic cases of inborn errors." (PMID 35546166, 2022). "One trial with the PPARα antagonist TPST-1120 as a monotherapy, and in combination with Nivolumab, Docetaxel or Cetuximab, in subjects with advanced cancers (NCT03829436) is ongoing." (PMID 35954274, 2022). "We roughly eliminated the possibility of PPARβ/δ and PPARγ being involved in cancer stemness using GSK3787/GW9662, and suggested that PPARα is necessary for the maintenance of stemness in pancreatic and colorectal CSCs." (PMID 33466690, 2021). "Subsequently, the bioinformatics analysis based on the IPA database revealed that the most enriched canonical signaling pathway is “PPARα/RXRα activation” and “AMPK signaling”, while the most enriched IPA disease and function is “cancer”." (PMID 33414423, 2021). "Nuclear receptors PPAR, in particular PPARα and PPARγ, and the receptor GPR55 can be considered targets of cannabinoids also in cancer." (PMID 34063214, 2021). "The expression patterns of PPARA (p < 0.001), PPARD (p < 0.001), PPARG (p < 0.001), PPARGC1A (p < 0.001), and PPARGC1B (p < 0.001) varied in 6 immune subtypes in pan-cancers." (PMID 33029111, 2020). "Actually, studies have confirmed that activation of PPARα suppressed HIF-1α signaling in human breast (MCF-7) and ovarian (A2780) cancer cells under hypoxia." (PMID 32963130, 2020). "In this study, we analyzed the expression signatures of PPARA, PPARD, PPARG, PPARGC1AA, and PPARGC1B in pan-cancer." (PMID 33029111, 2020). "The three PPAR subtypes (PPARα, PPARγ, and PPAR β/δ) are often activated in tumors, where they modulate cell survival, differentiation, and proliferation, critical aspects of cancer biology." (PMID 31775380, 2019). "PPARα-induced autophagy significantly inhibited tumor growth and enhanced SW480 cancer cell sensitivity to chemotherapy drugs." (PMID 30519260, 2018). "In agreement with these previous findings, our data demonstrate that in cancer cells, hypoxia-induced downregulation of FAO and reduction in expression of PPARα target genes both are dependent on HIG2." (PMID 29256392, 2017). "Taken together, these results indicate that HMGCS2 physically interacted with PPARα, which was bound to the Src promoter, enhancing its transcriptional activity and subsequently increasing OSCC and CRC cell motility and cancer metastasis." (PMID 27816970, 2017). "Thus, the exact role of PPARα and its ligands in cancer remains unclear." (PMID 27658584, 2016). "It has been shown that PPARα reduced cellular functions by attenuating IGF-1R and Akt activity in diverse cancer cells." (PMID 25695641, 2015). "Previous reports have shown that PPARα promotes apoptosis and inhibits cellular functions by IGF-1R signalling and Akt phosphorylation in various cancer cells." (PMID 25695641, 2015). "Our findings illustrate that PPARα is a potential tumor suppressor in HCC and raise the tantalizing possibility that PPARα has indeed therapeutic potential in treating this lethal cancer." (PMID 25327562, 2014). "Additionally, in mice, PPARα activation inhibits inflammatory gene expression by downregulation of acute phase proteins such as C-reactive protein (CRP), fibrinogen, and serum amyloid A (SAA) resulting in reduced hepatic inflammation and risk for cardiovascular disease and cancer." (PMID 20847941, 2010). "It is known that PPARα is expressed anddynamically regulated in both ER-positive (MCF-7) and ER-negative (MDA-MB-231) humanbreast cancer cells." (PMID 18645617, 2008). "Whereasthese studies clearly suggest that PPARα activation might be beneficial in reducingcancer growth, studies from the Gonzales laboratory demonstrate that long-term administrationof certain PPARα agonists (clofibrate andWY14643) induces liver adenoma and carcinomas in rats and mice." (PMID 18725983, 2008).
cancer (continued). "Therefore, PPARα, in addition to NF-κB, may represent another example of an oncogenic protein with a dual role in cancer by controlling essential functions both in cancer cell-autonomous processes as well as processes in the tumor bed, such as inflammation and angiogenesis." (PMID 17327920, 2007). "Thus, we aimed to compare the effect of AA520 with a PPARα antagonist GW6471 on the MTT cell viability/toxicity assay in HCA7 cancer cells." (PMID 39660001, 2024). "PPARα and cyclooxygenase (COX)-2 are overexpressed in certain types of cancer." (PMID 39660001, 2024). "The expression of PPARA, PPARD and PPARG in a total of 32 types of cancers was determined." (PMID 38529307, 2024). "In 366 patients’ cases and the Cancer Cell Line Encyclopedia from Novartis and Broad Institute, which were analysed for mutations in CNR1, TRPV1 and PPARα, up to 3% were mutated (with no mutational hotspot)." (PMID 37237519, 2023). "In addition, PPARα in HCT-1, SW1, HeLa, and MCF-116 cancer cell lines reduced levels of the Glut480 (glucose transporter 7) protein." (PMID 37251321, 2023). "On further analysis, PPARα directly targeted the consensus PPRE motif in the Glut1 promoter region, inhibiting Glut1 transcription, which in turn led to a decrease in glucose inflow in cancer cells." (PMID 37251321, 2023). "Benzenesulfonimide PPARα antagonists block the link between the peroxisome proliferator-activated receptor (PPAR) and Nrf2 pathways in cancer, affecting the cell cycle at the G2/M checkpoint, reducing cancer cell proliferation, and increasing caspase-3 cleavage to promote pyroptosis." (PMID 37542283, 2023). "Overall, our findings suggest that RV directly modulates PPARα-mediated L1-RTP in somatic cells and that MAPK signaling interacts with SIRT6 closely and may play a role in preventing human diseases such as cancer." (PMID 35546166, 2022). "Although PPARα activation by Wy-14,643 did not alter proliferation of cancer cell lines in vitro, it reduced tumorigenesis in vivo through the inhibition of angiogenesis." (PMID 35954274, 2022). "We hypothesize that a crosstalk between the PPARA-ANGPTL4 pathway and cancer related pathways occurs during the regulation of lipid metabolism." (PMID 36153524, 2022). "PPARα modulation is therefore, nowadays, not considered as a safe therapeutic option in the setting of cancer." (PMID 35954274, 2022). "A recent study showed that UA (0-50 μM) may exert antiskin cancer effects by promoting AMPK and PPARα in Ca3/7 and MT1/2 premalignant and malignant skin cancer cell lines." (PMID 36092543, 2022). "Therefore, PPARα activation attenuates EGCG-induced HO-1 up-regulation and sensitizes cancer cells to EGCG." (PMID 36092543, 2022). "Additionally, association analysis of CMTM6 mRNA levels with Wnt target genes (TCF4, LEF1, CD-44, MMP14, ENC1, ID2, PPARA, and JAG1) from the cancer genome atlas HNSCC cohort using GEPIA showed a positive correlation (r > 0.2)." (PMID 33434185, 2021). "PPARα was activated in CSCs in which LDs accumulated, but not in non-CSCs, and pharmacological and genetic inhibition of PPARα suppressed cancer stemness." (PMID 33466690, 2021). "The results clearly demonstrate that low expression of ACOX2 in cancer cells significantly inhibits the expression of PPARA, but not PPARD and PPARG." (PMID 33414412, 2021). "We performed multidimensional analyses on PPARA, PPARG, PPARD, PPARGC1A, and PPARGC1B, including differential expression analysis in pan-cancer, immune subtype analysis, clinical analysis, tumor purity analysis, stemness correlation analysis, and drug responses." (PMID 33029111, 2020).
cancer (continued). "Here we found that PPARα significantly induced cancer cell autophagy, while it was independent of its transcription activity." (PMID 30519260, 2018). "Indeed, whereas the direct regulation of PPARα by miR-9 in human HCC cells was confirmed by luciferase reporter assay, molecular analysis of human Snu-449 and HepG2 cancer cell lines indicated an indirect role for miR-9 overexpression in PPARα downregulation." (PMID 28167956, 2017). "In summary, our study using clinical specimens, cellular experiments, and animal models suggest that HMGCS2 increases cancer cell invasion and metastasis ability via the HMGCS2/PPARα/Src signaling pathway, and plays in a ketogenesis enzymatic-independent manner." (PMID 27816970, 2017). "We report that in cancer cells, PA cycles back and forth from the cellular membrane to the nucleus, affecting the function of epidermal growth factor (EGF), in a process that involves PPARα/LXRα signaling." (PMID 27256981, 2016). "The results show that silence of PPARα did not affect cell viability, but significantly increased cancer cell viability in response to cytotoxic stimulation (camptothecin, toxal, cisplatin, etoposide)." (PMID 26556865, 2015). "Contrasting to the current literature in cancer cells whereby poly-ubiquitination and/or degradation of substrate has been reported, the lack of degradation of PPARα and PPARγ1 despite mono-di-ubiquitination differs significantly." (PMID 26215257, 2015). "In addition, the rest of TFs such as PPARG, PPARA, SMAD3, MYC, and STAT1 have been proved to be related to cancer progression." (PMID 26425543, 2015). "A number of subnetworks were over-represented with a certain therapeutic category, non-steroidal anti-inflammatory drug, anti-cancer drug and PPARα agonist." (PMID 25115450, 2014). "Activation of PPARα/γ, LXRα/β and GCR will block the NF-κB pathway and thus prevent cancer." (PMID 19436720, 2009). "In both cases, tumor growth was strongly suppressed irrespective of the PPARstatus of the cancer cells, indicating that host PPARα and PPARβ/δ are important determinants in tumor formation." (PMID 18615187, 2008). "For example, long-term administrationof a PPARα agonist induces the development ofhepatocarcinomas in mice but not in PPARα null animals, conclusivelydemonstrating that PPARα mediates these effects in promotingliver cancer." (PMID 18551185, 2008). "Even more, exosomes derived from cancer cells were shown to contain higher levels of fatty acids compared to non-cancerous cells and could induce PPARα activation in recipient dendritic cells, leading to immune evasion." (PMID 40325149, 2025). "There are also a few examples of PPARα/Sp-mediated responses, but not in a cancer cell context." (PMID 39858066, 2025). "Our results suggest that PHA665752 may activate the cell death of cancer cells by inhibiting the PPARα pathway independently rather than binding to PPARα directly." (PMID 39859448, 2025). "These compounds are used to target different nuclear receptors of cancer which includes peroxisome proliferator-activated receptor gamma (PPARγ), toll-like receptor 4 (TLR4), brain-derived neurotrophic factor (BDNF), and peroxisome proliferator-activated receptor alpha (PPARα)." (PMID 41459064, 2025). "Specifically, PPARα directly binds to the lncRNA Gm15441 promoter to upregulate its expression and attenuate hepatic inflammation by decreasing the NLR family pyrin domain containing 3 (NLRP3) inflammasome activation, which is known to play important roles in cancer." (PMID 39199690, 2024). "In this phase I first-in-human study, which is the first to report clinical data on PPARα modulation in solid tumors, we tested the hypothesis that inhibiting PPARα with TPST-1120 would be tolerable in patients with advanced cancer and would have anticancer activity." (PMID 38551394, 2024).
cancer (continued). "Rodent data suggests that DEHP induces cancer through non-genotoxic mechanisms related to multiple molecular signals, including PPARα activation, perturbation of fatty acid metabolism, induction of cell proliferation, decreased apoptosis, production of reactive oxygen species, and oxidative stress." (PMID 39109301, 2024). "However, given that a substantial number of research works also propose the opposite, and advise the use of PPARα inhibition to provoke apoptosis in tumor cells, no clear recommendation for therapeutic PPARα modulation in cancer treatment can be postulated." (PMID 35954274, 2022). "Our results implied that PEPE2 might dysregulate the proteins involved in cell apoptosis, cell proliferation, death receptor signaling, JAK/STAT signaling, PPAR pathway, PPARα/RXR α pathway, Rho family GTPase signaling, and RhoGDI signaling to provoke cancer cell apoptosis." (PMID 36362994, 2022). "Furthermore, GW6471 treatment induced the inhibition of 6.5/cancer cell growth but did not alter 7.4/cell proliferation further supporting a major role of FA-induced PPARα activity under acidic conditions." (PMID 31974393, 2020). "With the exception of three clusters of NRs representing NR classes I (cluster I: RORC, VDR, PPARA, NR1D1, THRA, RORA, NR1H3; cluster II: RARB, PPARG, THRB) and III (cluster III: ESR1, PGR, AR, ESRRG), NR class was not a good determinate of NR expression patterns in the different cancer types." (PMID 32024906, 2020). "To support this hypothesis, we treated 6.5/cancer cells with GW6471, an antagonist of PPARα (a major FA-activated transcription factor regulating FA metabolism) and showed that the expression of DGAT1 but also that of mitochondrial fatty acyl-CoA transporter CPT1 were decreased." (PMID 31974393, 2020). "If related NHRs, PPARα and HNF4, play similar roles in protecting mammalian cells under stress conditions, then this may have implications for efforts to therapeutically target these NHRs to treat age‐related diseases such as metabolic diseases and cancer." (PMID 29508513, 2018). "Similarly, the agonist enhanced cancer cell autophagy in a PPARα-dependent manner, which was also independent of PPARα transcription activity." (PMID 30519260, 2018). "Considering that cancer cells have been reported to increase fatty acid oxidation (FAO) for cell survival due to compromised glucose uptake and ATGL-PPARα signaling have been reported to mediate FAO, we hypothesized that NEAT1 might serve as a means to mediate FAO through PPARα." (PMID 29764424, 2018). "Importantly, however, these chemicals do not induce cell proliferation in human cells in vitro or cancer in humans, suggesting significant differences between human PPARα and rodent Pparα-dependent regulatory pathways." (PMID 26122096, 2015). "Taking together, these data suggest that PPARα-mediated UCP2 upregulation might have a negative impact on cancer progression." (PMID 18509489, 2008). "Interestingly, the in vivoantitumor activity of PPARα agonists also depended heavily on the effects ofhost endothelial and stromal cells rather than cancer cells blocking angiogenesisand inflammation." (PMID 18551186, 2008). "To further strengthen our hypothesis that activation of the PPARα pathway by endogenous ligands leads to cancer cell proliferation and becomes dependent on this pathway, we compared the ability of PHA665752 and NSC3852 to kill cancer cells with different expression levels of PPARα." (PMID 39859448, 2025).